COL4A4 (collagen type IV alpha 4 chain)
Description:
Type IV collagen is the major structural component of glomerular basement membranes (GBM), forming a 'chicken-wire' meshwork together with laminins, proteoglycans and entactin/nidogen.
Synonyms: CA44; ATS2; BFH; BFH1
Tractability: Small molecule: a structure with a bound ligand is known. Antibody: a drug acting on it is in phase 1 trials; its Gene Ontology location is reachable by antibodies, with high confidence; UniProt places it where antibodies can reach, with medium confidence; UniProt predicts a signal peptide or a membrane-spanning region. PROTAC: ubiquitination databases record sites on it. Other modalities: an approved drug acts on it.
Target class: Structural protein
Gene: Protein-coding gene on chromosome 2 (227,002,714 to 227,164,453, reverse strand). Ensembl gene ENSG00000081052.
Subcellular location: Secreted, extracellular space, extracellular matrix, basement membrane
Pathways (Reactome):
Extracellular matrix organization: Anchoring fibril formation; Assembly of collagen fibrils and other multimeric structures; Collagen biosynthesis and modifying enzymes; Collagen chain trimerization; Collagen degradation; Crosslinking of collagen fibrils; ECM proteoglycans; Fibronectin matrix formation; Integrin cell surface interactions; Laminin interactions; Non-integrin membrane-ECM interactions
Developmental Biology: NCAM1 interactions
Disease: Attachment of bacteria to epithelial cells
Signal Transduction: Signaling by PDGF
Gene Ontology:
Molecular function: extracellular matrix structural constituent; molecular adaptor activity; extracellular matrix structural constituent conferring tensile strength
Biological process: glomerular basement membrane development; collagen fibril organization
Cellular component: basement membrane; collagen type IV trimer; extracellular matrix; endoplasmic reticulum lumen; extracellular region; collagen trimer
Genetic constraint (gnomAD): Loss-of-function variants: 86 observed, 169.43 expected, observed/expected ratio (o/e) 0.51, 90% interval 0.43 to 0.61. The upper end of that interval is the gene's LOEUF score, 0.61, which puts it in group 2 of 6, group 1 being the genes least tolerant of losing a copy. Missense variants: 1,802 observed, 2,081.2 expected, observed/expected ratio (o/e) 0.87, 90% interval 0.83 to 0.9. Synonymous variants: 708 observed, 748.54 expected, observed/expected ratio (o/e) 0.95, 90% interval 0.89 to 1.01.
Gene-disease validity (ClinGen):
ClinGen rates the evidence that COL4A4 causes each of these diseases.
Alport syndrome (semidominant): Definitive. A rare renal disease characterized by glomerular nephropathy with hematuria progressing to end-stage renal disease (ESRD), frequently associated with sensorineural deafness, and occasionally with ocular anomalies.
Homologues: Orthologues: chimpanzee COL4A4 (99% identical), macaque COL4A4 (96% identical), dog COL4A4 (83% identical), rabbit COL4A4 (82% identical), pig COL4A4 (82% identical), guinea pig COL4A4 (81% identical), mouse Col4a4 (78% identical), rat Col4a4 (78% identical), zebrafish col4a4 (47% identical), Caenorhabditis elegans emb-9 (43% identical), Drosophila melanogaster vkg (40% identical). Paralogues in human: COL4A6 (50% identical), COL4A2 (41% identical), COL4A5 (40% identical), COL4A1 (39% identical), COL4A3 (38% identical), COL5A1 (34% identical), COL11A1 (33% identical), COL11A2 (32% identical), COL5A2 (31% identical), COL5A3 (31% identical), COL7A1 (31% identical), COL2A1 (31% identical), and 25 more.
Diseases named in the same sentence as COL4A4 in open-access papers:
COL4A4 is named in the same sentence as 107 diseases in open-access papers, as found by Europe PMC text mining. Sharing a sentence is not in itself a finding about the gene and the disease. The quoted sentences say what the papers report.
Alport syndrome (145 papers, 2009 to 2026). "Pathogenic variants in COL4A3 and COL4A4 cause autosomal forms of Alport syndrome (autosomal dominant or recessive), while pathogenic variants in COL4A5 cause X‐linked Alport syndrome." (PMID 40317772, 2025). "The re-evaluation of the renal biopsy and subsequent genetic testing revealed the coexistence of a heterozygous pathogenic COL4A4 variant (G912R), indicating a concurrent diagnosis of Alport syndrome." (PMID 41516147, 2025). "Subsequent genetic testing confirmed a heterozygous pathogenic COL4A4 variant (G912R), indicating coexistence of Fabry disease and autosomal dominant Alport syndrome." (PMID 41516147, 2025). "This study investigated genotype–phenotype correlations and the distribution of COL4A3/COL4A4 variants in a Lithuanian Alport syndrome cohort." (PMID 40806767, 2025). "Variants in COL4A3 and COL4A4 cause autosomal dominant and recessive Alport syndrome, yet data on their distribution and clinical expression in different populations remain limited." (PMID 40806767, 2025). "The COL4A4 pathogenic variant causes autosomal recessive Alport syndrome, which is responsible for most genetic kidney failures in the Roma population." (PMID 40724130, 2025). "These ultrastructural findings prompted us to perform genetic testing for Alport syndrome, which revealed a heterozygous pathogenic variant, G912R, in the COL4A4 gene." (PMID 41516147, 2025). "In our study, utilizing whole exome sequencing (WES) and Sanger sequencing, we identified a novel mutation in COL4A4 (c.817-1 G > A) in an affected individual from a Chinese family with a history of Alport syndrome (AS)." (PMID 40406358, 2025). "AD Alport syndrome with heterozygous COL4A3 or COL4A4 variants typically results in haematuria, and sometimes FSGS but without a hearing loss or ocular abnormalities." (PMID 37578539, 2024). "The same authors identified another pathogenetic variant in COL4A4 gene (which encodes the collagen type IV alpha 4 chain) in a patient with Alport syndrome complicated by a SCAD event." (PMID 38399505, 2024). "Col4a2, Col4a3, and Col4a4 are associated with Alport's syndrome, a condition characterized by progressive hearing loss." (PMID 38413848, 2024). "Although Col4a4 is widely regarded as a pathogenic factor in diseases such as Alport syndrome (progressive glomerulonephritis, lens defects, and hearing loss), it has rarely been regarded as a contributing factor in AMD or CNV." (PMID 37025993, 2023). "The COL4A4 variants exhibit either dominant or recessive inheritance patterns, with the phenotype of dominant Alport syndrome being less severe in terms of a lower occurrence of kidney failure and older age of onset." (PMID 37895203, 2023). "The most controversial is autosomal dominant Alport syndrome (ADAS) in patients with heterozygous mutation in COL4A4 or COL4A3 gene." (PMID 36982595, 2023). "Autosomal recessive inheritance caused by mutations in the COL4A3 or COL4A4 genes accounts for approximately 15% of Alport syndrome cases." (PMID 40625571, 2023). "Bi-allelic variants in COL4A3 and COL4A4 cause autosomal recessive Alport syndrome, characterized by progressive kidney failure, sensorineural hearing loss, and ocular abnormalities." (PMID 36925663, 2023). "One girl (case 35) had a Pathogenic variant in COL4A4 leading to the diagnosis of autosomal recessive Alport syndrome." (PMID 37464296, 2023). "COL4A4 variant carriers also showed higher odds of hypertensive disease, consistent with nephritic syndrome commonly observed in Alport’s syndrome patients (MIM #203780), and lower hemoglobin concentrations and hematocrit percentage, consistent with hematuria." (PMID 36890159, 2023). "The aim of this report was to describe the identification of three new disease-causing variants in COL4A4, suspected to be founder variants, in the Bukharian Jewish population with autosomal dominant and recessive Alport syndrome." (PMID 37895203, 2023).
Alport syndrome (continued). "We next wished to determine if col4a3- and col4a4-deficient zebrafish model had increased levels of proteinuria, which is a feature of Alport syndrome." (PMID 35716957, 2022). "Heterozygous pathogenic COL4A3 and COL4A4 variants affecting Gly (n = 304) in autosomal dominant Alport syndrome were correlated with the risk of haematuria in the UK 100,000 Genomes Project." (PMID 35177655, 2022). "Many more variants have been reported for COL4A5 than for COL4A3 and COL4A4 because genetic testing has been performed more often for individuals suspected of having X-linked Alport syndrome." (PMID 35602506, 2022). "Monoallelic deleterious variants in COL4A3 and COL4A4 cause autosomal dominant forms of Alport syndrome (AS)." (PMID 36013122, 2022). "One year later, the proband was provisionally diagnosed with Alport syndrome after a variant of uncertain significance in the COL4A4 gene was identified following targeted family variant testing of her daughter." (PMID 35842573, 2022). "Autosomal dominant (AD) Alport syndrome is caused by a heterozygous pathogenic variant in COL4A3 or COL4A4 and associated with isolated haematuria and a thinned rather than lamellated membrane." (PMID 35602506, 2022). "Patients with isolated microscopic hematuria and heterozygous variants in COL4A3 or COL4A4 are considered to have autosomal dominant Alport syndrome (ADAS), which therefore eliminates the diagnosis of thin basement membrane nephropathy (TBMN)." (PMID 35547199, 2022). "The situation is more complicated in recessive Alport syndrome by the requirement for two COL4A3 or COL4A4 variants in trans." (PMID 33854215, 2021). "In 677 patients with a priori clinical diagnosis of GN, pathogenic variants in COL4A5, COL4A3 or COL4A4 were detected confirming the diagnosis of Alport syndrome or TBMN." (PMID 36939782, 2021). "Autosomal recessive Alport syndrome (ARAS) is caused by pathogenic variants in both alleles of either COL4A3 or COL4A4 genes." (PMID 33772369, 2021). "Mutations of COL4A5 on the X chromosome, as well as mutations of COL4A3 and COL4A4 on chromosome 2, can cause both Alport Syndrome and FIgAN." (PMID 34717572, 2021). "With the rapid development of molecular genetic testing, Alport syndrome causes have been restricted mostly to variants in the COL4A5 or COL4A3/COL4A4 genes." (PMID 34238373, 2021). "In autosomal recessive Alport syndrome (ARAS) with variants in the COL4A3 or COL4A4 genes, female and male patients are equally affected and also reach ESRD early in life." (PMID 34209341, 2021). "If every person with a heterozygous COL4A3 or COL4A4 mutation were labelled with the diagnosis of Alport syndrome, its incidence would increase from the current level of 1 in 5–10,000 to as high as 1 in 100, with ESKD being uncommon." (PMID 31044288, 2020). "Both thin basement membrane nephropathy (TBMN) and autosomal dominant Alport syndrome (ADAS) are types of hereditary nephritis resulting from heterozygous mutations in COL4A3 or COL4A4 genes." (PMID 32232700, 2020). "Mutations in COL4A5, COL4A3, and COL4A4, the three Alport syndrome genes, have been reported in patients presenting as FSGS." (PMID 31049720, 2020). "The diseases associated with heterozygous mutations in COL4A3 or COL4A4 genes are thin basement membrane nephropathy and autosomal dominant Alport syndrome." (PMID 30883042, 2019). "Here, we present a case of a two-year-old boy with autosomal recessive Alport syndrome (ARAS) caused by a novel c.193-2A>C COL4A4 mutation." (PMID 31686460, 2019). "Patients with XLAS who also had heterozygous pathogenic COL4A3 or COL4A4 variants accounted for 1% of Alport syndrome." (PMID 30883042, 2019). "In conclusion, we reported six XLAS children with heterozygous pathogenic COL4A3 or COL4A4 variants, which accounted for 1% of Alport syndrome." (PMID 30883042, 2019). "Germline variants in collagen type IV α-4 (COL4A4) gene lead to autosomal recessive Alport syndrome." (PMID 30745910, 2018).
Alport syndrome (continued). "This study confirmed that COL4A5, and COL4A3 and COL4A4 mutations in Alport syndrome all resulted in end-stage renal failure at the same age." (PMID 27627812, 2016). "Twenty COL4A3 or COL4A4 mutations were identified in the LOVD databases in individuals diagnosed clinically with autosomal dominant Alport syndrome." (PMID 27627812, 2016). "We will understand better genotype-phenotype correlations for heterozygous COL4A3 and COL4A4 mutations in Thin basement membrane nephropathy, and any genetic distinctions from variants that cause autosomal dominant Alport syndrome." (PMID 27627812, 2016). "Founder mutations were reported in both COL4A3 and COL4A4 in autosomal recessive Alport syndrome and Thin basement membrane nephropathy." (PMID 27627812, 2016). "Many fewer DNA variants have been described for the COL4A3 and COL4A4 genes, presumably because autosomal recessive Alport syndrome is less common, and genetic testing is performed infrequently for Thin basement membrane nephropathy." (PMID 27627812, 2016). "Clinical features were compared between individuals with autosomal recessive Alport syndrome caused by COL4A3 or COL4A4 pathogenic mutations and those with X-linked Alport syndrome and COL4A5 mutations." (PMID 27627812, 2016). "In humans, defects in the COL4A3/COL4A4/COL4A5 complex are the major cause of Alport syndrome, which is associated with a loss of BM integrity." (PMID 26451951, 2015). "Type IV collagen alpha 3–5 networks play an especially important role in the basement membranes of the kidney, inner ear, and eye; COL4A4 mutations have been found to cause Alport syndrome and thin basement membrane nephropathy." (PMID 22723992, 2012). "This study aims to clarify the role of the COL4A4 c.817-1G > A mutation in Alport syndrome." (PMID 40406358, 2025). "Moreover, the re-evaluation of the renal biopsy revealed features suggestive of Alport syndrome, subsequently confirmed by genetic testing, which identified a heterozygous pathogenic variant, G912R, in the COL4A4 gene." (PMID 41516147, 2025). "First, a recent genetic study with ADPKD and Alport syndrome revealed that COL4A4 variants may confer susceptibility to cystic changes." (PMID 41450889, 2025). "Notably, the sequencing revealed a heterozygous COL4A4 variant of uncertain significance (VUS) in the context of Alport syndrome." (PMID 41450889, 2025). "Interestingly, a single patient formally diagnosed with symptomatic cCMV was also found to have a COL4A4 gene mutation associated with Alport syndrome." (PMID 38390978, 2024). "Heterozygous variants in COL4A3 or COL4A4 cause autosomal dominant Alport syndrome." (PMID 38765603, 2024). "Since carriers of COL4A4 variants resulting in dominant Alport syndrome have hematuria as a presenting symptom, individuals revealed to be carriers might benefit from improved follow-up and treatment." (PMID 37895203, 2023). "Our results confirm phenotypic precision, identifying one locus well known to have pleiotropic causality for hematuria and albuminuria which is COL4A4, implicated in a monogenic disorder called Alport syndrome, reported to follow autosomal dominant and recessive inheritance patterns." (PMID 37872228, 2023). "For example, in two children with CKD (case 36, 44) in whom etiology was unknown, diagnosis of Alport syndrome was made based on detection of homozygous pathogenic variant in COL4A4 and COL4A5 genes." (PMID 37464296, 2023). "Thus, the GLA c.460A>G, p.Ile154Val, is to be classified as a benign variant, whereas the COL4A4 c.1181G>T, p.Gly394Val confirms the diagnosis of autosomal dominant Alport syndrome in this patient." (PMID 37323669, 2023). "Moreover, heterozygous mutations of COL4A3 or COL4A4 are reported to cause autosomal dominant Alport syndrome (ADAS)." (PMID 36292665, 2022).
Alport syndrome (continued). "Thus, the new classification of Alport syndrome by “the Alport Syndrome Classification Working Group” published in 2018 can help to minimize diagnostic confusion of disorders arising from the COL4A3 or COL4A4 genes." (PMID 33772369, 2021). "Mutations of COL4A3 and COL4A4 on chromosome two are also common causes of Alport syndrome." (PMID 34717572, 2021). "Three modes of inheritance exist for AS: X-linked Alport syndrome (XLAS) (mutations involving COL4A5 on the X chromosome), autosomal recessive Alport syndrome (ARAS) (mutations in COL4A3 or COL4A4 on chromosome 2), and autosomal dominant Alport syndrome (ADAS) (mutations in COL4A3 or COL4A4)." (PMID 34858896, 2021). "Some congress participants subscribed to the view that anyone with a heterozygous COL4A3 or COL4A4 mutation should be diagnosed with Alport syndrome, to ensure that the significance of their diagnosis is appreciated and to ensure aggressive management and long-term monitoring." (PMID 31044288, 2020). "Mutations in the COL4A3 and COL4A4 genes are the cause of autosomal recessive Alport syndrome (ARAS) (OMIM203780), with symptoms similar to those in male XLAS patients and autosomal dominant thin basement membrane disease, with a varying but usually milder phenotype." (PMID 33233744, 2020). "Some of the loci contain biologically plausible candidates in addition to the known CUBN (cubilin) locus: for example, rare mutations in COL4A4 (Collagen Type IV Alpha 4 Chain) cause Alport syndrome, a monogenic disease of basement membranes that frequently leads to end-stage kidney disease." (PMID 31511532, 2019). "Alport syndrome results from mutations in the COL4A5 (X-linked) or COL4A3/COL4A4 (recessive) genes." (PMID 27627812, 2016). "Our study finds that the COL4A4 c.817-1G > A variant may cause autosomal dominant Alport syndrome." (PMID 40406358, 2025). "Alterations in the COL4A3, COL4A4 and COL4A5 genes are associated with glomerular basement membrane-related diseases, such as autosomal recessive Alport syndrome, familial focal segmental glomerulosclerosis, and thin basement membrane nephropathy." (PMID 40351420, 2025). "The COL4A5 gene resides on the X chromosome and causes X-linked Alport syndrome, while the COL4A3 and COL4A4 genes are both located on chromosome 2, resulting in an autosomal dominant or recessive mode of inheritance." (PMID 40004525, 2025). "Our study provides important insights into the genetic landscape of Alport syndrome, confirming the central role of COL4A5 variants in X-linked inheritance and the involvement of COL4A3 and COL4A4 genes in autosomal forms." (PMID 40004525, 2025). "Pathogenic variants in type IV collagen genes (COL4A3, COL4A4, COL4A5) are classically associated with Alport syndrome (AS), a hereditary nephropathy primarily affecting the glomerular basement membrane (GBM)." (PMID 40565535, 2025). "Among the probands with a clinical suspicion of Alport syndrome and detected changes, we revealed monoallelic variants in the COL4A3 or COL4A4 gene in 27% (29/109)." (PMID 40004525, 2025). "Regarding the other mutated genes, as reported in the literature, the ones related to Alport syndrome (COL4A3, COL4A4) can be associated with kidney cysts." (PMID 39928271, 2025). "In summary, identifying P/LP variants in COL4A3, COL4A4, or COL4A5 during reproductive carrier screening provides an important opportunity for early clinical intervention for Alport syndrome heterozygotes and their families." (PMID 40317772, 2025). "Alport syndrome is caused by loss-of-function variants in one of the genes encoding the type IV collagen α3α4α5 network—COL4A3, COL4A4, or COL4A5." (PMID 41417821, 2025). "Alport syndrome is a rare genetic disorder resulting from the mutations in the genes COL4A3, COL4A4, and COL4A5 that affect the synthesis, assembly, deposition, or function of the glomerular basement membrane." (PMID 40212398, 2025).